GLRX5 (glutaredoxin 5)
Description:
Monothiol glutaredoxin involved in mitochondrial iron-sulfur (Fe/S) cluster transfer. Receives 2Fe/2S clusters from scaffold protein ISCU and mediates their transfer to apoproteins, to the 4Fe/FS cluster biosynthesis machinery, or export from mitochondrion. Required for normal regulation of hemoglobin synthesis by the iron-sulfur protein ACO1.
Synonyms: C14orf87; PR01238; GRX5; FLB4739; PRO1238; PRSA; SIDBA3; SPAHGC
Tractability: Small molecule: a structure with a bound ligand is known; it has a high-quality binding pocket. PROTAC: its protein half-life has been measured.
Gene: Protein-coding gene on chromosome 14 (95,533,503 to 95,544,724, forward strand). Ensembl gene ENSG00000182512.
Subcellular location: Mitochondrion matrix
Subcellular location (Human Protein Atlas): Mitochondria
Pathways (Reactome):
Metabolism: Mitochondrial iron-sulfur cluster biogenesis
Gene Ontology:
Molecular function: iron-sulfur cluster chaperone activity; protein binding
Biological process: [2Fe-2S] cluster assembly; erythrocyte differentiation; protein maturation; sulfate ion homeostasis; cell redox homeostasis; hemopoiesis; intracellular iron ion homeostasis; iron-sulfur cluster assembly
Cellular component: iron-sulfur cluster assembly complex; mitochondrial matrix; mitochondrion; dendrite; neuronal cell body
Genetic constraint (gnomAD): Loss-of-function variants: 9 observed, 8.55 expected, observed/expected ratio (o/e) 1.05, 90% interval 0.63 to 1.74. That is too few expected variants to judge how well the gene tolerates losing a copy. Missense variants: 230 observed, 165.19 expected, observed/expected ratio (o/e) 1.39, 90% interval 1.25 to 1.55. Synonymous variants: 98 observed, 74.94 expected, observed/expected ratio (o/e) 1.31, 90% interval 1.11 to 1.55.
Homologues: Orthologues: chimpanzee GLRX5 (100% identical), macaque GLRX5 (99% identical), dog GLRX5 (94% identical), guinea pig GLRX5 (92% identical), pig GLRX5 (92% identical), mouse Glrx5 (91% identical), rabbit GLRX5 (91% identical), rat Glrx5 (90% identical), tropical clawed frog glrx5 (66% identical), zebrafish glrx5 (61% identical), Drosophila melanogaster Grx5 (50% identical), Caenorhabditis elegans glrx-5 (39% identical). Paralogues in human: GLRX3 (35% identical).
Diseases named in the same sentence as GLRX5 in open-access papers:
GLRX5 is named in the same sentence as 51 diseases in open-access papers, as found by Europe PMC text mining. Sharing a sentence is not in itself a finding about the gene and the disease. The quoted sentences say what the papers report.
sideroblastic anemia (12 papers, 2010 to 2025). "Two patients with neurological phenotypes have been reported since then and one patient with sideroblastic anemia reported in association with missense mutations in GLRX5." (PMID 34732213, 2021). "The consistent and predictable neurological phenotype in patients with p.K51del GLRX5 mutations is in stark contrast to the pyridoxine resistant sideroblastic anemia reported in association with missense mutations of GLRX5." (PMID 34732213, 2021). "The first reported case of sideroblastic anemia from GLRX5 deficiency was due to mutation in the first exon of the GLRX5 gene that interferes with RNA splicing." (PMID 34732213, 2021). "Defects in δ–Alas2, Abcb7 [ATP-binding cassette, sub-family B (MDR/TAP), member 7], Glrx5 [glutaredoxin 5 homolog (S. cerevisiae)] and Slc25a38 (solute carrier family 25, member 38) are causal to different forms of sideroblastic anemias." (PMID 24124461, 2013). "However, several studies have also identified distinctive tissue-specific manifestations as the main characteristic in a number of disorders caused by variants in the Fe-S biogenesis components, including the sideroblastic anemia caused by loss of function in glutaredoxin 5 (GLRX5) (OMIM #616860)." (PMID 38950322, 2024). "In contrast, however, deficiencies in proteins responsible for ISC transfer, such as GLRX5, HSPA9, and HSCB, have been tightly linked with sideroblastic anemia phenotypes." (PMID 38757931, 2024). "In fact, the responsiveness to pyridoxine seen in XLSA also helps to distinguish it from other congenital causes of inherited sideroblastic anemia with mutations in SLC25A38, ABCB7, GLRX5, PUS1, and SLC19A genes." (PMID 39995829, 2024). "The occurrence of pyridoxine resistant sideroblastic anemia is discernible given the role of GLRX5 in both mitochondrial and cytosolic Fe homeostasis." (PMID 34732213, 2021). "Isolated sideroblastic anemia was first reported in a single patient with a GLRX5 messenger RNA splcing defect." (PMID 34732213, 2021). "Tissue-specific defects in mitochondrial ISC synthesis have more recently been identified in patients with isolated myopathy or sideroblastic anemia, which are linked to mutations in the scaffold ISCU and the enzyme glutaredoxin 5, respectively." (PMID 24624085, 2014). "Consistent with the zebrafish studies, RNAi knockdown of GLRX5 in K562 cells markedly reduced ALAS2 expression, and deficiency of GLRX5 in a patient caused by an intronic mutation that caused missplicing significantly increased the IRE-binding activity of IRP1, and caused sideroblastic anemia." (PMID 24982634, 2014). "Bi-allelic pathogenic variants in the gene encoding GLRX5, a protein involved in the early steps of Fe-S cluster biogenesis, are rare and cause two distinct phenotypes: isolated sideroblastic anemia and a neurological phenotype with variant non-ketotic hyperglycinemia." (PMID 34732213, 2021). "A similar observation stands true regarding glutaredoxin 5 (an assembly factor for cellular ISC), as a mutation in the exon 1 of the GLRX5 gene, putatively leading to a deleterious splicing defect, results in sideroblastic anaemia without ataxia and no overlap with the FA phenotype." (PMID 21985033, 2011).
iron overload (5 papers, 2011 to 2025). "Germline mutation in the Glutaredoxin 5 [GLRX5] gene causes iron overload and is associated with sideroblastic-like microcytic anaemia." (PMID 36408191, 2022). "The GLRX5 mutated patient is hallmarked by mild microcytic anemia, iron overload, and ring sideroblasts." (PMID 34946818, 2021). "Splicing defect in GLRX5 has been shown to cause severe anemia, enlargement of liver and spleen, and hepatic iron overload associated with cirrhosis." (PMID 26808690, 2016). "Thus, a detailed analysis of the association of ALR deficiency, changes in insulin levels, iron overload and fibrosis/cirrhosis with GLRX5 and hepcidin reduction in the presence of underlying liver injury warrants future investigation." (PMID 26808690, 2016).
anemia (4 papers, 2010 to 2019). A reduction in the number of red blood cells, the amount of hemoglobin, and/or the volume of packed red blood cells. "Deficiency of glutaredoxin 5 (GLRX5), a scaffold protein required for mitochondrial Fe-S cluster synthesis, activated IRP1, which inhibited ALAS2 translation and subsequently led to anemia in zebrafish, suggesting a role of IRP1 in coordinating Fe-S cluster and heme synthesis." (PMID 24982634, 2014).
head and neck cancer (4 papers, 2020 to 2022). A primary or metastatic malignant neoplasm affecting the head and neck. "Here, we examined the role of GLRX5 functional loss in promoting ferroptosis in cisplatin-resistant head and neck cancer (HNC) cells." (PMID 32685019, 2020). "We examined the role of GLRX5 functional loss in promoting ferroptosis in cisplatin-resistant head and neck cancer (HNC) cells." (PMID 32685019, 2020). "Inhibition of GLRX5 predisposes cisplatin-resistant head and neck cancer cells to ferroptosis." (PMID 36338346, 2022). "Silence of GLRX5 can reverse cisplatin resistance of head and neck cancer (HNC) cells through inducing ferroptosis." (PMID 34113488, 2021). "New studies have demonstrated that inhibiting GLRX5 induces ferroptosis in cisplatin-resistant head and neck cancer cells, suggesting a new therapeutic strategy for overcoming head and neck cancer chemoresistance through promoting ferroptosis by inhibiting GLRX5." (PMID 36338346, 2022). "GLRX5 knockdown could enhance intracellular lipid peroxidation and increase intracellular free iron, which is attributed to the upregulated transferrin and downregulated ferritin in head and neck cancer cells." (PMID 36230613, 2022).
Ataxia (3 papers, 2011 to 2021). Ataxia refers to impaired coordination of voluntary muscle movement. "These include mutations in ALAS2 (5′-aminolevulinate synthase 2) seven-codon in X-linked SA, mutations in ABCB7 in X-linked SA with spinocerebellar ataxia, and mutations in GLRX5 (glutaredoxin 5) in congenital SA, among many others (for a recent review, see Cazzola and Malcovati 2015)." (PMID 27151974, 2016). "Among those are Friedreich’s ataxia, glutaredoxin-5-deficient sideroblastic anemia, ISCU myopathy, and ABCB7 sideroblastic anemia/ataxia syndrome." (PMID 34946818, 2021).
Congenital sideroblastic anemia (3 papers, 2021 to 2024). "Congenital sideroblastic anemia (CSA) is most frequently caused by X-linked mutations in ALAS2 (Delta-aminolevulinate synthase 2, XLSA), followed by ABCB7 (ATP Binding Cassette Subfamily B Member 7), SLC25A28 (Solute Carrier Family 25 Member 28) and GLRX5 (Glutaredoxin 5)." (PMID 33672223, 2021).
Leukoencephalopathy (3 papers, 2018 to 2021). This term describes abnormality of the white matter of the cerebrum resulting from damage to the myelin sheaths of nerve cells. "It is also a quite common finding in Iron-sulfur cluster related leukoencephalopathies, particularly those caused by GLRX5, ISCA2, or IBA57 mutations." (PMID 29615062, 2018). "Similar to DARS-associated leukoencephalopathy, findings in GLRX5 associated neurological disorder might confuse neurologists toward diagnosing an acquired inflammatory disorder." (PMID 34732213, 2021). "Recessive mutations in GLRX5 induce nonketotic hyperglycinemia with neurodegeneration, leukoencephalopathy, optic atrophy, and spastic paraplegia in childhood." (PMID 33426505, 2020).
Sepsis (3 papers, 2019 to 2025). Sepsis is defined as life-threatening organ dysfunction caused by a dysregulated host response to infection. "In this study, we found that the low expression of GLRX5 in sepsis patients is associated with prognosis." (PMID 38755528, 2024). "In this study, we identified for the first time that four mitochondrial genes (FIS1, FKBP8, GUK1, GLRX5) can significantly impact the prognosis of sepsis patients, with high sensitivity and specificity for sepsis." (PMID 38755528, 2024). "Mitochondria-related genes (FIS1, FKBP8, GLRX5, GUK1) were underexpressed in the sepsis group, negatively correlated with survival, and mainly distributed in immune cells." (PMID 38755528, 2024). "We compared the gene expression levels of both groups and found that FIS1, FKBP8, GLRX5, and GUK1 were underexpressed in the sepsis group but overexpressed in the SIRS group." (PMID 38755528, 2024).
diabetes (2 papers, 2018 to 2022). "A human subject suffering from Glrx5 deficiency was reported to present anemia, type 2 diabetes mellitus/type 3c diabetes mellitus (i.e., by damage to the exocrine pancreas), hepatosplenomegaly, and cirrhosis of the liver due to cellular iron overload." (PMID 35453472, 2022). "In summary, we provide evidence that Glrx5 is regulated by FFA in type 2 diabetes mellitus and is linked to mitochondrial dysfunction and blunted insulin secretion." (PMID 35453472, 2022). "We deliver further evidence for the role of Glrx5 in β-cell deficiency in type 2 diabetes mellitus." (PMID 35453472, 2022). "Thus, glutaredoxin 5-deficiency in islets during diabetes may be caused by lipotoxicity and hypoxia." (PMID 29593651, 2018). "We have provided evidence that islet cells are deprived of Glrx5, correlating with impaired insulin secretion during diabetes in genetically obese mice." (PMID 35453472, 2022). "Islets of db/db mice presenting with uncontrolled diabetes were assessed in terms of morphological structure and insulin, glucagon, and glutaredoxin 5 expression." (PMID 29593651, 2018).
lactic acidosis (2 papers, 2017 to 2021). Metabolic acidosis characterized by the accumulation of lactate in the body. "However mitochondrial respiratory enzymes levels in patients with GLRX5 mutations have been reported to be normal when analysed in fibroblasts and patients who lacked lactic acidosis." (PMID 34732213, 2021).
microcytic anemia (2 papers, 2013 to 2021). Anemia in which the red blood cell volume is decreased. "Thus far, a single patient with GLRX5 inactivating mutations has been described, who is hallmarked by mild microcytic anemia, iron overload, and ring sideroblasts." (PMID 23917168, 2013). "Thus, mutations in genes that interfere with mitochondrial iron transport (e.g., mitoferrin) or FeS cluster biogenesis (e.g., GLRX5, ABC7) can cause microcytic anemias in animal models and/or patients." (PMID 23917168, 2013).
optic atrophy (2 papers, 2020 to 2021). A disorder characterized by loss of optic nerve fibers. "Surprisingly, the neurological phenotype of GLRX5 mutation, comprising myelopathy and variable leukoencephalopathy, seizures, optic atrophy and peripheral neuropathy, is reminiscent of other multiple mitochondrial dysfunction syndromes caused by defects in late acting ISC proteins." (PMID 34732213, 2021).
developmental delay (1 paper, 2024). "We identified a new case of GLRX5-mediated NKH who presented at 2-month with severe developmental delay and seizures." (PMID 39323869, 2024).
hypochromic anemia disease (1 paper, 2014). "The shiraz (sir) zebrafish mutants were originally isolated from the Tübingen 2000 screen consortium; these mutants were later identified as a typical hypochromic anemia disease model with a deletion in the glutaredoxin 5 (grx5) gene which encodes an antioxidant protein." (PMID 24639652, 2014).
Impaired glucose tolerance (1 paper, 2022). An abnormal resistance to glucose, i.e., a reduction in the ability to maintain glucose levels in the blood stream within normal limits following oral or intravenous administration of glucose. "The animals featured a considerable loss of islet Glrx5 concomitant with elevated serum FFA, obesity, and impaired glucose tolerance after HFD feeding." (PMID 35453472, 2022). "The HFD induced a depletion of islet Glrx5 concomitant with an obese phenotype, elevated FFA in serum and reactive oxygen species in islets, and impaired glucose tolerance." (PMID 35453472, 2022).
melanoma (1 paper, 2025). A malignant, usually aggressive tumor composed of atypical, neoplastic melanocytes. "Analysis of the TCGA-SKCM and GTEx datasets revealed elevated expression of NF2, SUZ39H1, CDC25A, GLRX5, and CISD3 in melanoma tissues, in contrast with the reduced expression of VDR, PPARD, CAMKK2, NT5DC2, and CHP1A." (PMID 40860143, 2025).
T-cell leukemia (1 paper, 2018). A malignant disease of the T-lymphocytes in the bone marrow, thymus, and/or blood. "The most significant SNP marker at 14q32.13 (rs117410836) is located near an uncharacterized long non-coding RNA (lncRNA; LINC02318), GLRX5 (glutaredoxin 5), and members of the T-cell leukemia (TCL) gene family (TCL1A, TCL1B, and TCL6)." (PMID 30305637, 2018).
cancer (4 papers, 2020 to 2024). A tumor composed of atypical neoplastic, often pleomorphic cells that invade other tissues. "Mutations in GLRX5 can also affect the production of downstream ISCs, leading to chemoresistance to cisplatin in various cancer cells." (PMID 37345031, 2023). "The present study has newly found the therapeutic possibility of GLRX5 inhibition predisposing therapy-resistant cancer cells to ferroptosis." (PMID 32685019, 2020). "The present study showed the role of GLRX5 functional loss in promoting ferroptosis in therapy-resistant cancer cells." (PMID 32685019, 2020). "Therefore, our study showed a new therapeutic potentiality of GLRX5 inhibition predisposing therapy-resistant cancer cells to ferroptosis." (PMID 32685019, 2020). "Rationale: Loss of iron-sulfur cluster function predisposes cancer cells to ferroptosis by upregulating iron-starvation response, but the role of glutaredoxin 5 (GLRX5) silencing in ferroptosis remains unknown." (PMID 32685019, 2020). "Therefore, our data suggested that GLRX5 inhibition predisposes therapy-resistant cancer cells to ferroptosis." (PMID 32685019, 2020). "GLRX5 gene silencing also induced significantly increased lipid ROS production in the SAS-treated cancer cells compared with vector control (P < 0.01)." (PMID 32685019, 2020). "Thus, inhibiting GLRX5 may induce ferroptosis in cisplatin-resistant cancer cells, presenting a promising therapeutic strategy to overcome chemoresistance by promoting ferroptosis via GLRX5 inhibition." (PMID 37345031, 2023). "Previous studies showed GLRX3, GLRX5, WRNIP1, THOP1, and HSCB were all regulators of various cancer occurrence and progression." (PMID 34078439, 2021).
tumor (2 papers, 2020 to 2025). "Representative images of protein expression in tumor tissues showed the accordance with the in vitro results of iron-starvation response boosted up by the GLRX5 silencing (increased TfR1, decreased Fpn)." (PMID 32685019, 2020). "The end product of lipid ROS, MDA concentrations in tumor tissues treated by SAS were more increased when tumors experienced GLRX5 silencing." (PMID 32685019, 2020). "In mouse tumor xenograft models, Glutaredoxin 5 (GLRX5) was shown to mediate ferroptosis." (PMID 41306421, 2025).
head and neck tumor (1 paper, 2022). "The inhibition of GLRX5 enhances ROS level and lipid peroxidation, thereby predisposing to ferroptosis in therapy-resistant head and neck tumor cells." (PMID 36352396, 2022).
GLRX5 also shares sentences with these, for which no sentence is quoted: infection (6 papers); bacteremia (4); Friedreich ataxia (3); abscess (2); infective endocarditis (2); myopathy (2); neurological diseases (2); Spastic paraplegia (2); type 2 diabetes (2); cardiovascular disease (1); cellulitis (1); Cirrhosis (1); colorectal carcinoma (1); cyst (1); dental caries (1); endocarditis (1); fibrosis (1); hepatocellular carcinoma (1); Hyperglycemia (1); ISCU myopathy (1); liver cancer (1); mitochondrial dysfunctions (1); multiple mitochondrial dysfunction syndromes (1); Myelopathy (1); Nonketotic hyperglycinemia (1); peripheral neuropathy (1); rickettsia infection (1); skin infection (1); Spasticity (1); spotted fever (1).
A further 1 disease shares a sentence with GLRX5 in 1 paper.